IL10 (interleukin 10)
Diseases named in the same sentence as IL10 in open-access papers (continued):
Sharing a sentence is not in itself a finding about the gene and the disease.
prostate carcinoma (continued). "In addition, previous studies have shown that IL-10 secreted by M2 TAMs plays an important role in the growth of various tumors, such as prostate cancer and intrahepatic cholangiocarcinoma." (PMID 39073672, 2024). "Tuft cells in mouse models of prostate cancer express Il25, and Il10 that may have immunosuppressive roles, as well as enzymes for eicosanoid synthesis for production of other immunomodulatory molecules." (PMID 37386128, 2023). "We also show vaccines targeting nonmutated prostate cancer associated proteins inhibit tumor growth only if IL-10 inducing epitopes are edited from the vaccine." (PMID 35948756, 2022). "According to previous studies, such mutation pattern in protein IL-10 contributes to the anti-tumor immune responses in prostate cancer but not in other tumor types, corresponding with our prediction." (PMID 34513841, 2021). "Abnormal levels of inflammation-related serum proteins, such as C-X3-C motif chemokine ligand 1, platelet-derived growth factor subunit B homodimer, interleukin 10, C-C motif chemokine ligand (CCL) 21, and CCL 11, were also found to be related to the risk of prostate cancer." (PMID 32722165, 2020). "Thus current study was designed to explore the association of various modes of tobacco exposure with proinflammatory (IL-12) and anti-inflammatory (IL-10) levels and survival in prostate carcinoma patients." (PMID 25177683, 2014). "Present study was conducted in densely populated North Indian region to explore the association of inflammation with various modes of tobacco exposure in prostate carcinoma patients and their survivals by measuring the serum IL-12 (proinflammatory) and IL-10 (anti-inflammatory) cytokine levels." (PMID 25177683, 2014). "Our results did not support a role for IL-10 SNPs in developing PCa, but as IL-10 expression alters according to cancer grade, our data suggest that IL-10 expression may impact prostate cancer progression." (PMID 20735825, 2010). "Presumably, this difference between IL-10E1 and CRP2 or hsmlim might explain why IL-10E1 is overexpressed in prostate cancer cells and functions as an IL-10-responsive signal molecule." (PMID 12771930, 2003). "Prostate cancers have also been shown to secrete factors such as transforming growth factor beta (TGFβ), interleukin-10 (IL-10), and vascular endothelial growth Factor (VEGF), constructing an immunosuppressive milieu that may demonstrate resistance to immunotherapy." (PMID 37762648, 2023). "Anti-inflammatory IL-10 may be selected as an anti-cancer agent for treating prostate cancer." (PMID 33807287, 2021). "Our results further suggest that IL-10 may be further selected as an anti-prostate cancer agent." (PMID 33807287, 2021). "In contrast, IgA+ plasma cells expressing IL-10 or programmed death ligand 1 (PD-L1) dismantle the antitumor immunity of T cells in HCC and prostate cancer, whereas they are involved in the protective humoral response in ovarian cancer 58,60,68." (PMID 39744696, 2025). "Gene expression of the immunosuppressive cytokines, IL-10 and TGF-β, were increased in canine prostate cancer compared with that in normal tissues." (PMID 35131860, 2022). "Another study also reported the absence of correlations between pretreatment and post-treatment serum concentrations of IL-4, IL-6, IL-10, and TNF-α, and fatigue symptoms in a group of 29 prostate cancer patients treated with radiotherapy." (PMID 36368974, 2022). "In this study, IL-8 and IL-10 mRNA expression and secretion levels in THP-1-derived M2 macrophages increased in the culture media of prostate cancer PC-3 cells." (PMID 35955737, 2022). "We provide evidence of immunomodulatory intervention of MGF-AuNPs in prostate cancers through observations of enhanced levels of anti-tumor cytokines (IL-12 and TNF-α) with concomitant reductions in the levels of pro-tumor cytokines (IL-10 and IL-6)." (PMID 34408231, 2021).
prostate carcinoma (continued). "We have previously shown that the STAT3 inhibitor galiellalactone inhibits cytokines such as GM-CSF and IL8 from prostate cancer cells and IL1ß, IL6 and IL10 secretion from monocytes." (PMID 33786638, 2021). "Moreover, our results suggest that some individuals develop antigen-specific IL-10 secretion to distinct tumor-associated antigens and not others, but overall that preexisting immune responses to two or more prostate cancer-associated proteins (AR, PAP, and/or PSA) were common (83% of individuals)." (PMID 28716080, 2017). "Furthermore, IFN-γ secreted by natural killer (NK) cells, along with high expression of IFN-γ, TNF-α, IL-5, IL-10, and macrophage inflammatory protein-1 alpha (MIP-1α), has been observed in castration-resistant prostate cancer." (PMID 40430079, 2025). "In prostate cancer, apolipoprotein E (APOE) in the TME binds to TREM2 on macrophages and promotes androgen receptor (AR) expression, which further upregulates the transcription of immune mediators such as IL-10, TGF-β1, IL-23A, and CCL2." (PMID 41417432, 2025). "In line with our observed effects of serum from exercise-trained pancreatic and prostate cancer patients, the growth of BC cells was notably inhibited when supplemented directly with recombinant myokines C-X-C motif ligand 1 (CXCL1), Interleukin 10 (IL10), and C-C motif chemokine ligand 4 (CCL4)." (PMID 39518934, 2024). "Albeit this role of APRIL for production of IL-10 by IgA+ Bregs, some other studies identified TGF-β as potent stimulatory factor for differentiation of immunosuppressive plasma cells which express IgA, IL-10 and PD-L1 in a mouse model of prostate cancer." (PMID 37849749, 2023). "Consistent with the findings that prostate cancer can secret certain factors, including IL-10, to induce M2 polarization, the authors further demonstrated that RSV is capable of inhibiting M2 differentiation by downregulating IL-10 secretion." (PMID 33535458, 2021). "In a study on prostatic cancer, it was postulated that immunosuppressive IgA+ plasma cells within tumors induced CD8+ cell exhaustion and suppressed anti-tumor cytotoxic T cell responses through PD-L1 and IL-10." (PMID 33121116, 2020). "In a follow-up study, IL-10 blocked IGF-1-induced MMP-2 mRNA expression and protein synthesis in primary prostate cells, implying that regulation of MMP expression in prostate cancer cells is a complex interaction of various cytokines present in the tumor microenvironment." (PMID 24978435, 2014). "Commensurate with our findings, two observational studies demonstrated that sequence variants detected in IL10 (rs1800871, rs1800872) and IL8 rs4073 were not significantly related to prostate cancer risk." (PMID 24359571, 2013). "We also describe evidence of immunomodulatory intervention of MGF-AuNPs in prostate cancers through observations of enhanced levels of anti-tumor cytokines, such as IL-12 and TNF-α, with concomitant reductions in the levels of pro-tumor cytokines, such as IL-10 and IL-6." (PMID 34408231, 2021). "But IL10 also exerts direct effects on nonimmune cells such as prostate cancer epithelial cells." (PMID 32802517, 2020). "However, to delineate the importance of IL-10 in the immunosuppressive effect mediated by MDSCs through STAT3, Hellsten and colleagues have demonstrated that inhibition of STAT3 using galiellalactone prevented the generation of MDSC-like cells from treated prostate cancer ex vivo." (PMID 32931721, 2020).
glioblastoma (71 papers, 2012 to 2025). The most malignant astrocytic tumor (WHO grade IV). "The results of the ROC, AUC, and RR analysis of IL-1β, IL-6, IL-8, and IL-10 indicated a potential diagnostic value for clinical prognosis in patients with glioblastoma (RR > 2)." (PMID 38003396, 2023). "Kaplan–Meier analysis of 540 glioblastoma cases from the Glioblastoma tumor RNA-Sequence dataset we identified showed a negative association between levels of gene expression of IL-4, IL-10, CCL-2, GM-CSF, and VEGF and overall survival." (PMID 35884700, 2022). "IL-10 is also directly implicated in glioblastoma cell growth and proliferation." (PMID 33803414, 2021). "Interestingly, the anti-inflammatory cytokine IL-10 is increased in the glioblastoma patients which has already been reported in association with immunosuppression in glioblastoma, whereas TNFα serum levels were unaltered." (PMID 31155685, 2019). "ICOSLG is expressed on GBM tumor cells, its upregulation being associated with the presence of glioblastoma stem cells and IL-10-producing T cells as well as the mesenchymal phenotype." (PMID 40895574, 2025). "Further, TAMs in glioblastoma predominantly exhibit an immunosuppressive phenotype, secreting factors such as IL-10 and TGF-β, thereby supporting immune evasion and tumor growth." (PMID 40676060, 2025). "Glioblastomas reprogram T cells into dysfunctional or pro-tumor states, recruiting Tregs that secrete immunosuppressive cytokines (IL-10, TGF-β), suppressing CD8+ T cells and promoting glioblastoma survival." (PMID 40443668, 2025). "Recent studies have shown that IL-10 significantly enhances the invasive potential and migration of U-87 glioblastoma cells in vitro." (PMID 40497976, 2025). "Consistent with this, recent spatial transcriptomics studies show that the necrotic and perinecrotic regions in glioblastoma are enriched for immunosuppressive signalling pathway signatures, including IL10 signalling." (PMID 40610434, 2025). "Downstream VEGF downregulation reprograms vasculature normalization to improve immune infiltration, collaborating with IL‐6 and IL‐10 reduction to develop anti‐glioblastoma responses." (PMID 38923275, 2024). "Efficient STAT3 gene editing downregulated VEGF, IL‐6, and IL‐10 to reprogram disordered vasculature and the immunosuppressive microenvironment for glioblastoma therapy." (PMID 38923275, 2024). "These predictive models were used to predict the impact of IL-10 signaling in the TME of glioblastoma, demonstrating a stabilization of cytotoxic T cells after IL-10 signaling inhibition." (PMID 38814900, 2024). "Astrocytes can produce immunomodulatory substances such transforming growth factor- (TGF-β) and interleukin-10 (IL-10), which dampen the immune response to glioblastoma cells." (PMID 38523646, 2024). "The downregulation of downstream vascular endothelial growth factor (VEGF) reprograms vasculature normalization to improve immune infiltration, collaborating with interleukin‐6 (IL‐6) and interleukin‐10 (IL‐10) reduction to develop anti‐glioblastoma responses." (PMID 38923275, 2024). "In contrast, THP-1 cells co-cultured with compensatory overexpressed (OE)-KDELC2 glioblastoma cells increased IL-10 secretion, a biomarker of M2 macrophages." (PMID 37107298, 2023). "EZH2 is involved in glioblastoma-induced immunosuppression, it induces IL-10 as well as TGF-β secretion in glioblastoma cells and attenuates microglia phagocytosis and shifts toward the M2 phenotype." (PMID 37700840, 2023). "Vidhya M found that IL‐10 release drives T‐cell exhaustion in glioblastoma, thereby contributing to an immunosuppressive TME." (PMID 36856182, 2023). "Tumor associated macrophages (TAMs) contribute to the malignant features of glioblastoma by secreting pro-tumorigenic factors, e.g., IL-10 and TGF-β." (PMID 37228396, 2023). "Increased levels of IL-10 are known in patients with glioblastoma, what makes this parameter important for evaluation in this work." (PMID 36986829, 2023).
glioblastoma (continued). "Within glioblastoma tumours, exposure to IL-10 upregulates PD-L1 expression on GAMs, with the functional consequence of inducing T cell apoptosis." (PMID 33803414, 2021). "IL-10 mRNA expression is found to be elevated in glioblastoma, with M2-like GAMs and GSCs reported to contribute to its production." (PMID 33803414, 2021). "Cells in the glioblastoma microenvironment release cytokines such as TGFβ, interleukin-10 (IL-10) and VEGF, which have immunosuppressive roles." (PMID 31979318, 2020). "For example, PD-L1 has been shown to be upregulated in glioblastoma cells as well as circulating monocytes and macrophages through oncogenic signaling resulting from PTEN loss and modulation of autocrine–paracrine IL-10 signaling." (PMID 27774435, 2016). "Targeting TAMs to regulate IL-10 may enhance anti-tumor immunity, highlighting its therapeutic potential in glioblastoma." (PMID 40443668, 2025). "Importantly, PGE2 in glioblastoma cells increases the overexpression of immunosuppressive cytokines, such as interleukin 6 (IL-6), interleukin 10 (IL-10), and granulocyte-macrophage colony-stimulating factor (GM-CSF)." (PMID 32560280, 2020). "Similarly, naïve T cells were shown to differentiate into IL-10 and TGFβ secreting Treg cells, when co-cultured with TAMs from glioblastoma patients." (PMID 30853959, 2019). "In fact, findings on the importance of this polarisation process have not been only reported for CRC progression but also for other several cancers, such as glioblastoma, as a consequence of M2-macrophage production of important factors that augment tumour growth (e.g., IL-10)." (PMID 30285662, 2018). "In glioblastoma (GBM), p300 catalyzes lactate-driven histone lactylation in the promoter region of interleukin 10 (IL-10), increasing IL-10 expression, which inhibits T-cell activity and facilitates tumor immune escape." (PMID 40859309, 2025). "RNA sequencing analysis of samples from TCGA patients with glioblastoma (GBM) revealed that IL-10 expression was higher patients with GBM than in normal participants." (PMID 38521953, 2024). "Both TAMs and microglia are implicated in gliomagenesis in glioblastoma through several mechanisms including immune suppression and secretion of several soluble factors such as transforming growth factor-β (TGF-β) and interleukin-10 (IL-10) that can further exacerbate immunosuppressive state." (PMID 33202642, 2020). "Tregs ensure glioblastoma escape primarily by inhibiting CD8+ cytotoxic lymphocytes, secreting various soluble factors such as IL-10 and TGF-β." (PMID 40071070, 2025). "H3K18 lactylation enhances the transcription of LINC01127 and IL-10, with LINC01127 promoting glioblastoma cell self-renewal and IL-10 suppressing T cell activity in the glioblastoma microenvironment." (PMID 41373440, 2025). "Conversely, glioblastoma-derived factors, like TGF β, IL-10, prostaglandin E2, can lock DCs in a tolerogenic state characterized by PD-L1 expression and diminished IL-12 production, thereby dampening T cell activation." (PMID 40443668, 2025). "Despite their potential for anti-tumor activity, NK cells are found in low levels or impaired within glioblastoma tumors and thus their cytotoxic effects are suppressed by factors such as TGF-β and IL-10 within the TME." (PMID 41208963, 2025). "Factors including IL-10, IL-6, VEGF, GM-CSF, PGE-2, and TGF-β2, found upregulated in glioblastoma, also influence MDSCs expansion." (PMID 41208963, 2025). "M2-polarized microglia and macrophage, in turn, secrete immunosuppressive cytokines such as IL-8 and IL-10, VEGF, RANTES, MCP-3, GRO-α creating an immunosuppressive microenvironment that fosters glioblastoma progression." (PMID 39407269, 2024). "The concentrations of IL-1β, IL-6, IL-8, IL-10, TNFα, and HMGB1 confirmed that inflammation was a critical component of glioblastoma progression." (PMID 38003396, 2023).
glioblastoma (continued). "To assess the effects of dendrimers on IL-10 production, we have chosen NCH644 line as a representative example of glioblastoma stem-like cells." (PMID 36986829, 2023). "For example, tumor-infiltrating macrophages have been reported to blunt the antitumor response in glioblastoma by secreting TGF-β and IL-10 and recruiting regulatory T (Treg) cells." (PMID 36611973, 2023). "TGF, interleukin-10 (IL-10) and VEGF are immunosuppressive cytokines released by cells in the glioblastoma microenvironment." (PMID 35999629, 2022). "Anti-inflammatory molecules, such as IL-10, TGFβ, and MHC-II, which are increased in glioblastoma-activated pericytes, are responsible for tumor growth." (PMID 31861092, 2019). "The expression of anti-inflammatory molecules, such as IL-10, TGF-β, and MHC-II, is increased in glioblastoma-activated pericytes, thus favoring immunosuppression and tumor growth." (PMID 31861092, 2019). "Yet, a recent study demonstrates that post infusion of CAR T cells, tumor specimens in glioblastoma patients have markedly increased expression of many immunosuppressive molecules, particularly IDO1 and FoxP3, and in some cases, IL-10, PD-L1, and/or TGF-β." (PMID 29685162, 2018). "For example, in glioblastoma patients, levels of the immunosuppressive cytokines IL4 and IL10 were elevated in both their peripheral lymphocytes and cell cultures from their tumors." (PMID 28594935, 2017). "MDSCs are key players in glioblastoma immunosuppressive TME, exerting their effects via various mechanisms including amino acid depletion, oxidative stress, decreased DCs maturation, and the indirect induction of Tregs induced by IL-10 and TGF-β." (PMID 41208963, 2025). "In a mouse model of glioblastoma (GBM), the p300 inhibitor CPI-1612 was shown to eliminate histone lactylation and its mediated IL10 expression in monocyte-derived macrophages, thereby enhancing the efficacy of immunotherapy for GBM, while acetylation (Kac) modification levels remained unaffected." (PMID 39334941, 2024). "Glioblastoma exploits this malleability by enriching the local TME with immunomodulatory factors such as transforming growth factor β (TGF-β) and interleukin-10 (IL-10), which polarize TAMs to their immunosuppressive phenotype and reduce their antigen-presenting capabilities." (PMID 38132354, 2023). "Moreover, in the serum of patients with glioblastoma (the most typical parenchymal brain tumor), it has been reported that there is a significant overexpression of IL-6, IL-1β, TNF-α, IL-10, VEGF, FGF-2, IL-8, IL-2, and GM-CSF." (PMID 37368708, 2023). "Taken together, these results suggest that glioblastoma may cooperate with Treg cells via OX40L, thereby enhancing IL-10 production." (PMID 25744203, 2015). "Loss of MHC expression, immune suppressive cytokines (TGF-B, IL-10, PGE2), and the expression of PD-L1 in patients with glioblastoma (GBM) contribute to a TME enriched with immunosuppressive factors, rendering these individuals resistant to ICI therapy." (PMID 40492861, 2025). "A study in glioblastoma multiforme (GBM) found that TAMs with high PD-L1 expression were significantly related to M2 polarization, and secreted typical chemokines, TGF-β And IL-10." (PMID 38693304, 2024). "First, they demonstrated that Nano-reshaper remodeled the local glioblastoma microenvironment, rectifying abnormal blood vessel structure and decreasing levels of glioblastoma-derived immunosuppressive cytokines such as TGF-β and IL-10, resulting in lower levels of Tregs and M2 phenotype TAMs." (PMID 38132354, 2023). "Authors show here, using spatially resolved and single cell transcriptomics, that dysfunctional T cells are induced by a myeloid cell subset via Interleukin-10 signalling, and inhibition of the downstream JAK/STAT pathway might restore glioblastoma immune therapy responsiveness." (PMID 35177622, 2022).
glioblastoma (continued). "Previous studies indicated strong overexpression of IL-6, IL-10, VEGF, GM-CSF, and CCL2 in human GBM specimens, and the level of overexpression strongly correlated with tumor grade, proliferation markers, and clinical aggressiveness in glioblastomas." (PMID 35884700, 2022). "The unique immune-privileged microenvironment due to the inherent expression of immunosuppressive cytokines, such as PD-1, TGF-β, and IL-10, and the lack of antigen-presenting cells (APCs) in the CNS present obstacles for the efficacy of immunotherapy in glioblastoma (GBM)." (PMID 34220791, 2021).